CD44 (CD44 molecule (IN blood group))
Diseases named in the same sentence as CD44 in open-access papers (continued):
Sharing a sentence is not in itself a finding about the gene and the disease.
breast tumors (continued). "RNA expression of CD44 isoforms was investigated in a set of 187 primary breast tumors." (PMID 21957977, 2011). "Several groups identified a small subpopulation of highly tumorigenic cells from human breast tumors bearing the CD44+CD24-/low lineage phenotype, which have drug-resistant phenotype and the capacity to form tumors after transplantation in nonobese diabetic/severe combined immunodeficient mice." (PMID 18241344, 2008). "Thus, the resistance of HER2-high breast tumors to trastuzumab may be due to an increased population of HER2-low CD44+/CD24 mesenchymal cells at the late passages." (PMID 34575017, 2021). "Therefore, based on these observations, we hypothesized that CD44 down-regulates CD146 expression during breast tumor progression." (PMID 29121955, 2017). "Thus, in response to TME Stimulation, two cell sub-populations were enriched in MCF-7 and T47D Luminal-A breast tumor cells: cells with the CD44+/β1+ phenotype and cells with the CD44+/CD24low/− phenotype, the latter possibly representing a sub-population of CSCs." (PMID 27835603, 2016). "Furthermore, this newly-discovered HA/CD44-activated JNK/c-Jun signaling pathway and miR-21 production/function should provide important new drug targets to cause tumor cell apoptosis and overcome chemotherapy resistance in breast tumor cells." (PMID 24606718, 2014). "The prevalence of CD44+/CD24-/low cells within breast tumors, however, has not been significantly associated with clinical characteristics – although tumors with a higher fraction of CD44+/CD24- cells were more commonly found in patients diagnosed with distant metastases." (PMID 18559090, 2008). "Leveraging HA's intrinsic CD44 targeting, HA/PtP nanogel simultaneously enables highly efficient PTT and targeted chemotherapy in 4T1 breast tumor xenografts." (PMID 41849596, 2026). "Given that increased stem cell biomarker expression was observed in high NOS2 expressing ER- breast tumors, we measured CSC biomarker expressions (ALDH1A1, OCT4, CXCR4, CD133, CD117, CD44 and NANOG) in the control and DETANO treated MCF10A cells." (PMID 36830680, 2023). "The complex formation of glycoprotein CD44 and its ligand MMP-9 on the cell surface of breast tumor cells was found to promote ECM degradation, cell migration, invasion and metastasis, suggesting that the MMP-9/CD44 axis is a promising therapeutic target." (PMID 37185776, 2023). "Accumulation of hyaluronan and overexpression of its receptor CD44 and hyaluronidase TMEM2 in breast tumors correlate with tumor progression and reduced overall survival of patients." (PMID 36497283, 2022). "The correlation between an increase in the proportion of CSCs in breast tumour tissue and a poor prognosis increases when ALDH1 is used in combination with the CD44+CD24−/low phenotype." (PMID 35563449, 2022). "Our previous study has proven that activated HA/CD44 has activated PI3K signalling pathway to phosphorylate the transcription factor E2F1 promoting the expression of Survivin, resulting in breast tumour invasion." (PMID 36505828, 2022). "While CD44+ breast tumor-initiating cells can contribute to CTC cluster formation and lung metastasis of TNBC8, our work suggests that ICAM1 and CD44 independently direct cancer metastasis." (PMID 34381029, 2021). "The hyaluronan/CD44 signaling was also correlated to the activation of RhoA/ROCK pathway and subsequent the phosphorylation of NHE-1, leading to breast tumor cell invasion." (PMID 33407452, 2021). "The 3rd generation 3D breast tumor spheroids displayed a stemness phenotype, as assessed by the methylcellulose clonogenic assay, riboflavin uptake, HIF-2α and CD47, CD44, CD24, and CD133 CSC marker expression." (PMID 34205080, 2021). "Previous studies have shown an increase in CD44+/24− cells and high ALDH+ characteristics of tumor-initiating or cancer stem cells in breast tumors and established cell lines after irradiation." (PMID 33419140, 2021).
breast tumors (continued). "This study also examined the expression of CSCs markers (CD44 and CD24) and EMT markers (E-cadherin, β-catenin, vimentin, and N-cadherin) in the isolated breast tumor cells and in tumor tissues by qRT-PCR." (PMID 33282946, 2020). "For instance, Wright and colleagues reported that two distinct CD44+/CD24− and CD133+ cells with cancer stem cell characteristics were identified in Brca1 breast tumors." (PMID 32430004, 2020). "Cells with high CD44 and low CD24 expression (CD44+/CD24-) define a CSC-like population in breast tumors 20 that exhibits high tumorigenic potential and drug resistance." (PMID 31762819, 2019). "Recent data have shown that the JAK2/STAT3 pathway is preferentially activated in CD44 + CD24- breast CSCs through the excessive production of IL6 and promotes CSC growth in breast tumors." (PMID 31511084, 2019). "As CD44 is a stemness marker and is known to be associated with EMT32, and because we found that the expression of CD44 was reduced by NS1643 treatment, we speculated that NS1643 suppresses EMT, which in turn attenuates cancer stemness, thereby inhibiting breast tumor growth and metastasis." (PMID 30792401, 2019). "Most current studies have demonstrated CD44 and CD24 as proposed markers for isolation of CSC subset in breast tumors." (PMID 29552056, 2017). "Our results supported that luminal breast neoplasm tended to be with high DACH1 expression and low CD44 level, while basal-like tumors were most likely to be the inverse type." (PMID 28659634, 2017). "Thus, it is possible that when Luminal-A breast tumor cells are exposed to multiple factors of the TME simultaneously - as recapitulated in our study by the combined TME Stimulation - the CSC sub-population is enriched in parallel to the CD44+/β1+ sub-population." (PMID 27835603, 2016). "CD44 and ALDH1 were up-regulated in BORIS-depleted spheres of breast tumor cells (3.7 for MCF7, 1.5 fold for MDA-MB-231) but down-regulated in HT29 BORIS-depleted spheres." (PMID 26185996, 2015). "Our previous work indicated that HA/CD44-activated PKCε promotes Nanog interaction with p68 and DROSHA leading to biosynthetic processing and production of miR-21 in breast tumor cells." (PMID 24606718, 2014). "Further, our studies showed that VDR expression was suppressed while CD44 was up-regulated in transplantable xenografts (TX), ALDH+ population enriched in MCSCs as well as in aggressive breast tumors." (PMID 23341935, 2013). "This study also showed that MBCs and claudin-low subtype breast tumors have high levels of stem cell and EMT markers, and that the transcriptional features of these subtypes are enriched in CD44+/CD24−/low breast CSC/TICs." (PMID 24009024, 2013). "TN breast tumors expressed significantly lower VDR (76.4±6.2%) and higher CD44 (105.6±8.7%) expression compared to ER+ tumor groups." (PMID 23341935, 2013). "Double-staining immunohistochemistry was used to quantify CD44 and CD24 expression in 240 human breast tumors for which information on other tumor markers and clinical characteristics was available." (PMID 18559090, 2008). "Interestingly, YAP/TAZ and SOX2 were found to be significantly upregulated in the CD44+/CD24− and ALDH+ population isolated from patient breast tumors, adherent cells and mammospheres." (PMID 39979255, 2025). "For chemoresistance, the interaction of CD44 with p300 and SIRT1 is found to regulate β-catenin signaling and NFκB-specific transcription activity, leading to MDR1 and Bcl-xL gene expression and chemoresistance in breast tumor." (PMID 38542115, 2024). "MK-0752 is a gamma-secretase inhibitor, already with a phase II clinical trial completed, that showed promising results targeting BCSCs, since a decrease in CD44+CD24- population, as well as decreased mammosphere forming efficiency, was observed in samples from breast tumour serial biopsies." (PMID 35326385, 2022).
breast tumors (continued). "In breast tumor samples specifically, IHC showed that absence of CD44 correlated with low signal from 18F-FSPG-PET, even if the SLC7A11 subunit was present, indicating possible importance of CD44 co-expression for system xC- function." (PMID 35294486, 2022). "CSCs from breast tumors are suggested to have high expression of CD44 and low or no expression of CD24." (PMID 35012489, 2022). "We thus report that CD44 may impact on TF expression at a transcriptional level and modulate the coagulant activity of EMT+ breast tumor cells." (PMID 35805061, 2022). "Moreover, tumors or cell lines with low levels of SPN showed an enrichment of CD44+ CD24- cells 17, which have been proposed to be cancer-initiating cells in breast tumors 20,21." (PMID 33537097, 2021). "Although there have been conflicting reports about the role of CD44 isoforms on tumour phenotypes, we demonstrated that CD44v8‐10, but not CD44s, facilitated the resistance of canine breast tumour cells to H2O2 and radiation in this study." (PMID 33210459, 2021). "Furthermore, we observed an increase in the number of both CD105+ cells and CD44+/CD24− cells, confirming that treatment with conditioned media alone induces dedifferentiation of breast tumor cells." (PMID 33106480, 2020). "In breast tumor patients, both CK+CD44+CD24−/low CTCs, or CTCs expressing CD44, MET, and CD47, might represent CSCs." (PMID 30959764, 2019). "Interestingly, within the breast tumor heterogeneity, distinct bCSC types are found: CD24−/CD44+; ALDH+; and CD24−/CD44+/ALDH+, all with different features and transcriptomic profiles." (PMID 29734696, 2018). "To better investigate the role of PLC-β2 in modulating the stem cell phenotype of TNBC cells, we also evaluated the surface expression of CD44, a well-described cancer stem cell marker in breast tumors and a negative prognosticator in TNBC." (PMID 28870198, 2017). "The aim of this study was to validate CD146 as a negative transcriptional target of CD44-HA downstream signaling mediating breast tumor cell invasion." (PMID 29121955, 2017). "Two of the 51 mAbs, however, did inhibit coalescence in the screen, and did so completely, H4C4 against CD44, the hyaluronic acid receptor, and AIIB2, against beta-1-integrin (CD29), the mAb previously demonstrated to block coalescence of tumorigenic breast tumor-derived cells." (PMID 28264026, 2017). "In addition, selective inhibition of STAT3 by small molecule inhibitors suppresses CD44+/CD24−/ALDH+ BCSCs, mammosphere-forming efficiency and tumor growth in human breast tumor xenograft rodents." (PMID 28445439, 2017). "A high expression of CD44 paired with absent/low expression of CD24 on the cell surface has been used as a CSC marker in breast tumours." (PMID 28863191, 2017). "The interaction of CD44 and TGF-β pathways promoted breast tumor metastasis." (PMID 27769048, 2016). "In addition, human breast tumor-derived CTCs co-expressing E and M protein markers, such as EPCAM and CD44 have been shown to initiate metastases in mice." (PMID 26020648, 2015). "Indeed, VEGF C expression was found to correlate with the CD44+/CD24-low + mammosphere (MS) signature (Pearson's r = 0.61) and, importantly, also with gene sets that are upregulated in breast tumors after chemotherapy (Pearson's r = 0.51)." (PMID 25358638, 2014). "CD44 also interacts with MDR1 (P-gp) to promote cell migration and invasion of breast tumor cells." (PMID 24606718, 2014). "Breast tumor formation can be initiated by a small number of tumorigenic cells characterized as CD44+CD24lo/-, while non-tumorigenic cells are CD44-CD24+." (PMID 21605402, 2011). "A population of cells with a CD44+CD29hiCD133/2hi phenotype has also been identified in ERα-negative human breast tumours that was highly tumourigenic, capable of self-renewal and also expressed common stem cell markers." (PMID 24212798, 2011).
breast tumors (continued). "Recent studies reported that breast tumors may contain only CD44+, or only CD24+ cells, as well as mixed cell populations, and that CD44+ tumor cells express many stem-cell markers." (PMID 20585577, 2010). "It has been reported that CD44+/CD24−/low cells were more common in basal-like tumors and strongly associated with BRCA1 hereditary breast cancer; however, not every basal breast tumor contains CD44+/CD24−/low cells." (PMID 20027313, 2009). "Other recent studies have also shown that the presence of CD44+/CD24−/low cells in breast tumors did not correlate with clinical outcome including tumor size, lymph node status or S-phase fraction." (PMID 20027313, 2009). "A recent study demonstrated CD44+/CD24- cells in 59% of human breast tumors, further supporting that not all breast tumors contain cells with this phenotype." (PMID 18559090, 2008). "We also conducted a primary breast tumor tissue microarray (TMA) study and observed a correlation of CD44 and CD81 expression across tumor subtypes (TNBC, HER2, luminal A/B) as well as an upregulated expression of CD44/CD81 in TNBC in comparison to luminal A/B." (PMID 36193887, 2022). "Moreover, although dissimilar from the clinical setting in terms of expression of some markers, the results from in vitro analysis of EVs suggested the implication of CD44 and CD146 in biological processes involved in breast tumor and microenvironment interplay." (PMID 34820420, 2021). "Furthermore, the CD44+/CD90+ phenotypic signature indicative of tumorigenicity in cells separated from metastatic or primary breast tumors does not have the same significance in circulating tumor cells." (PMID 28721373, 2016). "Since CD44 and RHAMM functionally cooperate under certain conditions, targeting RHAMM may be an effective way to specifically limit the function of CD44 in breast tumors." (PMID 26106384, 2015). "Moreover, an increase in CD44+/CD24−/low-MS and claudin-low signatures was observed in post-treatment samples after chemo or hormone therapy, indicating that remaining breast tumors after conventional treatment are likely to be enriched in cell subpopulations with CSC/TIC features." (PMID 24009024, 2013). "In addition, basal breast tumors are characterized by low ER and PR expression as well as high levels of EGFR, elevated expression of AKT3, CD44 and MET and decreased GATA3 expression; features that are also consistent with each of the HER2 related subgroups investigated in the current study." (PMID 21672245, 2011). "Recently, in a breast tumor, a stem cell-like population, defined by the presence of CD44 and absence of CD24, has been identified, which might disseminate into the circulation and escape therapy, and presents an expression profile associated with metastatic relapse." (PMID 30959764, 2019). "Taken together, these findings strongly suggest that targeting HA/CD44-mediated JNK/c-Jun signaling pathways and miR-21 function may provide new drug targets to sensitize tumor cell apoptosis/death and overcome chemotherapy resistance in MDA-MB-468 breast tumor cells." (PMID 24606718, 2014). "Furthermore, the phenotype of breast tumour cells showed that CD44 may distinguish tumour-initiating from non-tumourigenic cells." (PMID 20565761, 2010). "In breast tumors, the cancer stem cells (CSC) can be identified by the expression ofCD44 and by low or absent expression of CD24 (CD44+/CD24-/low)." (PMID 31384244, 2019). "Although the relationship between CD44+/CD24−/low and the clinical outcome is not certain, breast tumors with expression of CD44+/CD24−/low have been shown to exhibit enhanced invasion and metastasis." (PMID 29062075, 2017).
breast tumors (continued). "When human breast tumors were propagated in non-obese diabetic severe combined immunodeficiency (NOD/SCID) mice, it was observed that as few as 100 of the CD44+CD24−/low cells were able to give rise to new tumors." (PMID 25905435, 2015). "In the non-breast tumor cells, HT29 and HeLa, no change of expression was observed with both cells displaying a typical CD44+/CD24- epithelial phenotype." (PMID 26185996, 2015). "Similar to the results of Honeth and co-workers, we found 35% of cases showing CD44+CD24-/low immunophenotype, suggesting that not all breast tumors contain cells with this phenotype, as described by Al-Hajj in 2003." (PMID 21824412, 2011). "The increase in the expression of CD44 and CD24 in the explant cultures that were generated from a broad range of breast tumour types, and not just the basal type, indicated a chemotherapy-induced expression of CD44Hi and CD24Hi cells rather than an enriching of the CSCs." (PMID 25669750, 2015). "Moreover, they also report that in MCF12A mammary epithelial immortalized cells, the CD44+/CD24-/low profile, found to enrich for cancer stem cells in primary breast tumors, failed to enrich for mammosphere initiating cells." (PMID 24124614, 2013). "This was further confirmed by immunofluorescence, where spheroids were labelled with CD44+/CD24−/low/ABCG2/KI67 for CSCs derived from breast tumors, and CD133+/CD44+/ABCG2/Ki67 for prostate and ovarian tumors; except for the prostate LnCap CSCs, which were not CD44+." (PMID 28536422, 2017).